HLA-C (major histocompatibility complex, class I, C)
Diseases named in the same sentence as HLA-C in open-access papers (continued):
Sharing a sentence is not in itself a finding about the gene and the disease.
tumor (continued). "For effective killing of tumors, CD8+ T cells recognize tumor peptides presented by molecules of human leukocyte antigen class I. In humans, there are three major HLA-I genes (HLA-A, HLA-B, and HLA-C)." (PMID 33416081, 2021). "Since the presence of the HLA-C*08:02 allele is requisite for the presentation of the neoantigen KRAS G12D and tumor recognition by T lymphocytes, its loss was supposed to directly cause immune evasion." (PMID 31963413, 2020). "The class-I HLAs of patient 01 were typed as HLA-A*11:01, HLA-A*02:10, HLA-B*40:01, HLA-B*40:01, HLA-C*08:01, and HLA-C*07:02, which were double-checked by assaying tumor and blood samples." (PMID 33208106, 2020). "MHC class I family mainly includes HLA‐A, HLA‐B, and HLA‐C, essential for endogenous antigen presentation of tumor cells and subsequent recognition by the immune system." (PMID 33252851, 2020). "The HLA-I expression type was determined by immunohistochemistry of HLA-A, HLA-B, HLA-C and β2-microglobulin in the centre of the tumour (CT) and in the invasive margin (IM) of samples from 293 patients (total loss vs. preserved type)." (PMID 32203213, 2020). "In CMV infected individuals, adaptive NK cells have enhanced capacities for antibody-dependent cellular cytotoxicity (ADCC) and are particularly responsive to modulation of HLA-C on the surface of tumor cells." (PMID 31623687, 2019). "Robust expression of MHC class I genes (HLA-A, HLA-B, and HLA-C) was seen in PA tumor and immune cells, suggesting that antigen presentation is intact." (PMID 31427603, 2019). "Objective regression was observed of lung metastasis after the infusion of HLA-C*8:02-restricted tumor infiltrating lymphocytes that were composed of four different T cell clonotypes that specifically targeted KRAS G12D." (PMID 35582274, 2019). "Lirilumab (IPH2102) and monalizumab (IPH2201) are IgG4 monoclonal antibodies (mAbs) currently in clinical development that target KIR2DL1-3 and NKG2A, and antagonize the inhibition of NK cells mediated by HLA-C and HLA-E on tumor cells, respectively." (PMID 30250471, 2018). "A similar case report of a resistant colorectal tumor found LoH in the HLA-C*08:02 region of tumor cells, which is required for KRAS G12D neoantigen presentation." (PMID 30497521, 2018). "We found that four out of the 21 shared ASE genes (HLA-A, HLA-B, HLA-C, and CEACAM7) and showed significant differences in the allele ratios between tumor and normal tissues (paired t-test)." (PMID 30538721, 2018). "It has been reported that tumoral cells can upregulate HLA-A, HLA-B and HLA-C expression, decreasing the level of macrophage activation." (PMID 29228712, 2017). "Lirilumab induced significant anti-tumor activity of NK cells against HLA-C-expressing tumor cells, contributing to increased survival in lirilumab-treated mice." (PMID 28620386, 2017). "Here, the expression of IP subunit PSMB8 correlated with RARRES3 in BM-MSC and four tumor datasets, and also correlated with HLA-C in all but one of these cancer types." (PMID 28051153, 2017). "We found that HLA-A, HLA-B, HLA-C genes have a similar pattern of reduction in CRPC and elevation in high risk NHT primary tumours." (PMID 27619158, 2016). "Given its dual functionality in interactions with innate and adaptive immunity, HLA-C plays a key role in immunosurveillance of both virally infected cells and recognition and elimination of tumor transformed cells." (PMID 25083782, 2014). "Collectively, cell activation potentiates ADCC, while HLA-C mismatched setting further enhances the specific tumor killing effect in an additive manner." (PMID 23483943, 2013). "Alterations in genes corresponding to major histocompatibility complex class I (eg, HLA-B or HLA-C) have been postulated to promote tumor evasion of immune surveillance (eg, by restricting neoantigen presentation), although no guideline recommendations to test HLA genes exist currently." (PMID 38508412, 2024).
tumor (continued). "Notably, tumor cells evade immune surveillance by down-regulating NK cells’ sensitivity and upregulating human leukocyte antigen C(HLA-C) and human leukocyte antigen E (HLA-E) expression." (PMID 38464531, 2024). "Low tumor expression of HLA-A, but not HLA-B or HLA-C, was significantly associated with favorable OS prognosis in GBM patients treated with TFDC immunotherapy (p = 0.014)." (PMID 37382632, 2023). "Notably, the expression of genes encoding MHC class I molecules, such as human leukocyte antigen (HLA)-A, HLA-B, HLA-C, and HLA-E, and beta-2 microglobulin, significantly decreased in After Tumor." (PMID 38136558, 2023). "Further studies may focus on the 2C/165 TCR due to its higher avidity that translated also into increased reactivity against HLA-C*07:01+/CSPG4+ tumor cell lines." (PMID 37849763, 2023). "Notably, NST ER−/HER2− cancer cells from obese patients expressed lower levels of major histocompatibility complexes class I (MHC-I) (HLA-B, HLA-C), suggesting a potential niche for evasion of anti-tumor immunity." (PMID 37479706, 2023). "Recently, a CD8+ T-cell reactivity against KRASG12D has been detected in tumor-infiltrating lymphocytes (TILs) from a patient with metastatic colon cancer, which could recognize and kill tumors in an HLA-C*08:02-restricted, KRASG12D-specific manner." (PMID 36384590, 2022). "Cultures were established in a 96-well microculture format to favor stimulation of rare peptide-dependent minor histocompatibility antigens (mHAg)- or tumor antigen-specific CTLs instead of allo-HLA-B or -HLA-C mismatch reactions, which would dominate in bulk MLTC." (PMID 35681710, 2022). "Notably, KIR blockade by another anti-KIR IgG4 mAb IPH2101 (1-7F9) has been shown to induce endogenous NK cell-mediated lysis of HLA-C-expressing tumor cells." (PMID 35174079, 2022). "However, one patient had progressed and the sequencing result revealed that this patient has lost the chromosome 6 haplotype encoding the HLA-C*08:02 class I major histocompatibility complex (MHC) molecule, providing a mechanism for tumor immune evasion." (PMID 33450833, 2021). "Thus, stimulation of NK cells via KIR2DS2 can generate anti-cancer reactivity against HLA-C expressing human tumor cells." (PMID 34016721, 2021). "HLA-C and B2M are required to present tumor neoantigens to cytotoxic CD8+T cells." (PMID 35173763, 2021). "Besides, the primary tumor of the right lower lobe was genotyped as HLA-A*02:03, HLA-A*11:01, HLA-B*55:02, HLA-B* 40:01, HLA-C*12:03, and HLA-C* 07:02 using a modified computing method." (PMID 34094914, 2021). "The relapse-free survival period was significantly associated with the expression of tumor immune response-related genes, such as IL1A, molecular identification group (MIG), TCR repertoire clonetype, and HLA-C expression, based on both Pearson_p-value and logrank_p-value." (PMID 33476333, 2021). "Our results do not allow us either to establish whether the effectors driving this phenomenon are NK cells or cytolytic T cells through the recognition of tumor peptides presented in HLA-C*04." (PMID 34064810, 2021). "The expression of T cell cytotoxicity (CD3G, CD3E, CD4, GZMA, PRF1 and TBX21), B cell MHC II and immune exhausted-related genes were abundant in metastatic sites; while MHC I inflammation related genes (HLA-B, HLA-C and IL-1A) were mostly higher in primary than recurrent tumor sites." (PMID 33476333, 2021). "CD8+ T cells recognize tumor peptides presented by major HLA-I genes (HLA-A, HLA-B, and HLA-C)." (PMID 33575208, 2020). "However, HLA-C is overexpressed on certain tumor cell lines, particularly Cw, which is accompanied with poor prognosis." (PMID 31013867, 2019). "Validation analysis indicated that HLA-C, HLA-DPA1, HLA-E, HLA-F and HLA-G were associated with HCC prognosis of overall survival (all P ≤ 0.05, elevated 0.988 and 0.997 multiples compared to non-tumor tissues, respectively)." (PMID 31602270, 2019).
tumor (continued). "Finally, we quantified the numbers of circulating tumor cells in the mice at the time of sacrifice on day 40 by measuring human HLA-C levels in whole peripheral blood by quantitative PCR." (PMID 23468956, 2013). "These individuals may also possess wider repertoire of HLA-C-educated NK cell clones which would eliminate these tumor cells which lost HLA-C expression." (PMID 23372569, 2013). "Angiogenesis-related genes (FLT1, KDR, SPARC, INSR, ANGPT2, and FLT4) and MHC-I molecules (HLA-A, HLA-B, HLA-C, HLA-E, and HLA-F) were highly expressed in cluster 3 ECs, indicating that the cells may function as antigen-presenting cells and promote tumor parenchymal angiogenesis." (PMID 37533434, 2023). "Furthermore, such CAR-NK cells could overcome inhibition by HLA-E or HLA-C expressed on tumor cells." (PMID 35585985, 2022). "Deep sequencing revealed that the tumor had lost a copy of chromosome 6 encoding HLA-C*08:02 so that adoptive TILs could not recognize the tumor, indicating the importance of HLA-restriction element expression." (PMID 35014625, 2022). "The tumor growth in HLA-C-high A2780 xenografts was inhibited compared to that in the control (50% reduction compared to that in the control); however, the inhibition was notably lesser than that observed in HLA-C-low A2780cis (80% reduction compared to that in the control; P * < 0.05)." (PMID 34686187, 2021). "Thus, individuals who have the KIR AA genotype in this population likely have two genomic copies of the strongly inhibiting KIR2DL1 allotype, KIR2DL1*003, and should be best equipped at recognizing and eliminating tumor cells having aberrant C2+HLA-C expression." (PMID 31379844, 2019). "This suggests that ADCC and HLA-C mismatching could be combined, and since both parameters can be controlled or selected, they reflect a novel opportunity to rationally maximize the anti-tumor effect." (PMID 23483943, 2013). "Therefore, we can imagine that in NSCLC patients, individuals with C1/C2 genotype may have wider repertoire of antigenic peptides, including tumor antigens, presented to their HLA-C-restricted CD8+ cytotoxic T cells which can eradicate tumor cells." (PMID 23372569, 2013). "Immune-related proteins were first analysed, and we revealed that IFN-γ increased not only tumour cell PD-L1 but also antigen peptide transporter 1 (TAP1), HLA-A, HLA-B, HLA-C and ICAM-1, indicating strong adhesion and enhanced immunogenicity." (PMID 38719909, 2024). "Conversely, DCs in solitary primary tumours showed high expression of MHC class I molecules (HLA‐F, HLA‐E, HLA‐C, HLA‐B, HLA‐A)." (PMID 39601163, 2024). "Tumor cells can express various MHC class I molecules (e.g., HLA-A, HLA-B, and HLA-C) on their surface, which present tumor-specific antigens to CD8+ T cells." (PMID 39014148, 2024). "Specifically, the involvement of human leukocyte antigen (HLA) class I molecules (such as HLA‐A, HLA‐B, HLA‐C, HLA‐E and HLA‐F) and CD8A/B was consistently observed in the interactions between malignant cells and CD8 T cells in both tumour types." (PMID 39601163, 2024). "Excitingly, both HLA-A and HLA-C, important subtypes of human MHC I molecules crucial for tumor recognition and T-cell-mediated elimination, were significantly down-regulated in our study." (PMID 39840062, 2024). "In contrast, aT-sEVs downregulated the expression of PD-L1, TAP1, HLA-A, HLA-B, HLA-C and ICAM-1 in tumour cells." (PMID 38719909, 2024). "The anti-KIR2DL1/2/3-mAb-IgG4 targets inhibitory KIR2DL1/2/3 receptors on NK cells and blocks their interaction with human leukocyte antigen (HLA)-C (classical MHC-I), thereby enhancing NK-mediated anti-tumor activity." (PMID 38272918, 2024). "This was further supported by the high levels of MHC I/II molecules (HLA–B, HLA-C, HLA-DRB1 and HLA-DQA1) expressed in cDC-CD1C-AREG from low tumor infiltration group as well as inflammatory cytokines and chemokines (IL1B, VEGF and CCL4, etc.)." (PMID 36532059, 2022).
tumor (continued). "Most MHC I molecules, including HLA-A, HLA-C, HLA-E, HLA-F, TAP1, TAP2, and TAPBP (all P < 0.05), were upregulated in PTPRD/PTPRT mutant patients, indicating enhanced anti-tumor immunity in PTPRD/PTPRT mutant patients." (PMID 36248841, 2022). "In the TCGA dataset, the expression levels of CD2, HAVCR2, HLA-C, HLA-DRA, HLA-E, KLRK1, and TYROBP were all significantly downregulated in tumor tissues compared with para-tumor tissues." (PMID 35794593, 2022). "Similar results were obtained for the other MHC class I genes HLA-B and HLA-C, suggesting that the immune system plays a role in controlling hypermutated MSI/CMS1 tumours in the early stages of the disease." (PMID 35747143, 2022). "We then explored the expression of the ULBP ligand family and HLA-C, which are NKG2D ligands known to augment NK cell activity and tumor immunity in vivo." (PMID 34926577, 2021). "Several genes of antiviral immune response pathways such as HLA-B, HLA-C, HLA-DQB1 IFI6, IFITM3, CD74, and tumor suppressor genes EFEMP1 and EGR1, are upregulated in tumor and downregulated in TAS." (PMID 34316327, 2021). "HLA-C and KIR2DL4 was one of the more significant immune cell-tumor interactions (on NK) during single-cell transcriptomic analysis of NPC." (PMID 33671917, 2021). "The first-in-class humanized IgG4 mAb IPH2101, targeting an epitope shared by KIR2D, was produced to block the binding of HLA-C to KIR2D to release NK cell inhibition and enhance NK cells' capacity to kill tumor targets." (PMID 32714324, 2020). "We used DNA isolated from pathological archival lymphoid and tumor tissues for KIR and KIR ligand (HLA-C, group C1, group C2, and HLA-A-Bw4) genotyping." (PMID 26181663, 2015). "In HLA-C, the region 1,500–200 bp upstream of the transcriptional start site (termed TSS1500) had the highest level of methylation, followed by the gene body, in both the tumor and normal tissues." (PMID 39358601, 2024). "We next tested the association of primary/metastasis-specific downregulation of an MHC class I metagene signature composed of a composite expression of HLA-A, HLA-B, HLA-C, B2M, TAP1, TAP2 and NLRC5 between metastasis and matched primary tumor according to intrinsic subtype." (PMID 36585450, 2023). "The expression levels of B2M(p = 2.926e-05), HLA-C(p = 2.628e-03), HLA-E(p = 5.5166e-08), HLA-F(p = 9.376e-03), TAP1(p = 1.972e-09), TAP2(p = 1.245e-04) and TAPBP (p = 2.652e-12)in tumor tissues of dMMR patients were significantly higher than those of pMMR patients." (PMID 36527024, 2022). "It has been reported that the absence of HLA‐I (e.g. HLA‐A, HLA‐B, HLA‐C) expression is a common finding in different tumor tissues and is a major mechanism used by tumor cells to escape T cell‐mediated immune surveillance." (PMID 35229456, 2022). "Lack of inhibitory input from tumor targets led to ADAPT-NK cell attack in HLA-C/KIR mismatched settings whereas tolerance to self was maintained in matched settings with high HLA-C expression." (PMID 36319065, 2022). "Tumor regions analyzed were either predicted to have all loci (HLA-A, HLA-B, and HLA-C) subject to LOH, or no loci affected." (PMID 29107330, 2017). "Furthermore, antigen-presenting molecules and immune molecular interactions, such as those between HLA-A, HLA-B, HLA-C, HLA-E, and HLA-F with CD8A and CD8B, appeared to be significantly up-regulated in tumor tissues, while their presence in normal tissues was comparatively diminished." (PMID 40723292, 2025). "Given the potential relevance of this response regarding tumor immunogenicity, and eventually for leveraging the efficacy of ICI-based therapies, we validated the effect of CM272 on the expression of chemokine CCL5 and different MHC genes such as HLA-A, HLA-B and HLA-C." (PMID 39810240, 2025). "Interestingly, this population of cells may also be involved in tumor antigen presentation, since genes for MHC-I molecules (HLA-A, HLA-B, HLA-C, HLA-E, and HLA-F) were highly expressed in this cluster." (PMID 37533434, 2023).
tumor (continued). "HLA-B and HLA-C also showed the sametrend but lacked statistical power due to the low number of peptides.The fold changes between tumor and paired normal samples are alsohighly consistent on RNA and protein levels, confirming that the overexpression waslargely driven at a transcriptional level." (PMID 37857377, 2023). "Moreover, the majority of PDS showed strong MHC-I expression and upregulated HLA class I molecules (HLA-A, HLA-B, HLA-C and HLA-E, corresponding in humans to the MHC class I) that are involved in tumor neoantigen presentation to tumor-specific CD8+ T lymphocytes leading to tumor cell apoptosis." (PMID 36465341, 2022). "As the ACT of T-cells genetically engineered to express tumor-reactive TCRs can elicit regression of widespread cancer in patients with metastatic disease, the TCRs isolated above may extend TCR gene therapy to HLA-C*08:02 patients whose tumor express KRASG12D, including AML patients." (PMID 36384590, 2022). "The lack of HLA-C and B2M limits the activation of tumor-infiltrating T cells." (PMID 35173763, 2021). "Furthermore, restoring the expression of MARC2 could increase the expression of HLA-C and B2M via PPARA-related lipid metabolism signaling pathways, which could facilitate tumor antigen presentation to the tumor-infiltrating T cells." (PMID 35173763, 2021). "However, the lack of expression of the HLA-C*08:02 molecule in a single lesion mediated tumor immune escape and resulted in tumor progression nine months after the treatment." (PMID 33654227, 2021). "In addition, HLA-DQA1 and HLA-F showed prognostic values for overall survival, and HLA-A, HLA-C, HLA-DPA1 and HLA-DQA1 showed prognostic values for recurrence-free survival (all P ≤ 0.05, elevated 0.927, 0.992, 1.023, 0.918, 0.937 multiples compared to non-tumor tissues, respectively)." (PMID 31602270, 2019). "The HLA-C*06:02 presented peptide SRGPVHHLL identified in this study mediated strong activation of primary NK cell clones, suggesting that this peptide could be potentially used to label specific tumors in order to enhance anti-tumor cytotoxic activity by KIR2DS1(+) NK cells." (PMID 28546555, 2017). "In CTCL, our findings show that all three classical MHC-I proteins (HLA-A, HLA-B, and HLA-C), but not the non-classical MHC-I (HLA-E), exhibit high expression levels on tumor T cells from MF skin lesions." (PMID 38272918, 2024). "Presence of somatic variants in genes related to antigen presentation, including HLA-A, HLA-B, HLA-C, B2M (β-2-microglobulin), TAP2, and PSMB8 (LMP-7), did not predict tumor classification." (PMID 30824826, 2019). "We did not observe a difference in tumor MHC class I expression according to DCB (HLA-A: n = 26, Mann-Whitney p = 0.26, HLA-B: n = 26, Mann-Whitney p = 0.36, HLA-C: n = 26, Mann-Whitney p = 0.24)." (PMID 28552987, 2017). "Analysis of a dataset of the International Cancer Genome Consortium (ICGC)/The Cancer Genome Atlas (TGCA) pan‐cancer whole genome analysis (n = 1210 samples, 23 tumor types) revealed a negative correlation of JARID2 mRNA levels with those of HLA‐A and HLA‐C mRNAs." (PMID 37452654, 2023). "They analyzed GSC derived from primary tumor samples by mass cytometry, and the GSC expressed normal levels of NK cell activation receptor ligands (ULBP2, ULBP3, VIM) and upregulated levels of NK cell inhibitory receptor ligands (HLA-A, HLA-B, HLA-C, HLA-E, HLA-G, PCNA) compared with non-GSC." (PMID 34638384, 2021).